ABCA1 (ATP binding cassette subfamily A member 1)
Diseases named in the same sentence as ABCA1 in open-access papers (continued):
Sharing a sentence is not in itself a finding about the gene and the disease.
triple-negative breast carcinoma (6 papers, 2020 to 2024). An invasive breast carcinoma which is negative for expression of estrogen receptor (ER), progesterone receptor (PR), and human epidermal growth factor receptor 2 (HER2). "ABCA1 previously was shown to be expressed in ADR-sensitive triple-negative breast cancer cells and in ADR-sensitive osteosarcoma cells." (PMID 38827789, 2024). "We found ABCA1 expressed in doxorubicin-sensitive osteosarcoma cells, in line with previous findings showing a constitutive expression of ABCA1 in doxorubicin-sensitive triple-negative breast cancer cells." (PMID 32155954, 2020). "Along with eicosapentaenoic acid, it is responsible for building up of ATP-binding-cassette-subfamily-A-member-1 (ABCA1)-dependent cholesterol, which increases the polarity of the plasma membrane and promotes apoptosis in triple-negative breast cancer (TNBC) cells." (PMID 36830852, 2023). "Similar observations have been made regarding ABCA1 suppression in triple-negative breast cancers, and together with the current study, indicate that for cancers that thrive in cholesterol-rich environments, disrupting cholesterol efflux may be a viable therapeutic strategy." (PMID 35454786, 2022).
age-related macular degeneration (5 papers, 2021 to 2025). Age-related loss of vision in the central portion of the retina (macula), secondary to retinal degeneration. "Lipid metabolism genes such as APOE, ABCA1, LIPC, and CETP play fundamental roles in the pathogenesis of age-related macular degeneration (AMD) by influencing lipid transport, cholesterol efflux, and lipoprotein remodeling within the retinal pigment epithelium (RPE) and Bruch’s membrane." (PMID 40331961, 2025).
aortic atherosclerosis (5 papers, 2011 to 2022). A atherosclerosis that involves the aorta. "It thus activates the accumulation of foam cells and macrophages; it further targets ATP-binding cassette transporter A1 (ABCA1) and causes development of aortic atherosclerosis." (PMID 33669699, 2021).
arteriosclerosis (5 papers, 2014 to 2024). A vascular disorder characterized by thickening and hardening of the walls of the arteries. "Additionally, we noticed the ABCA1 gene, located in the 54th position among 2,254 candidate regions, has been shown to reduce arteriosclerosis risk when up-regulated." (PMID 38982489, 2024). "It is important to highlight that ABCA1 plays a crucial role in lipid metabolism and exerts protective effects against arteriosclerosis." (PMID 39275180, 2024). "ABCA1-mediated cholesterol efflux leads to the formation of HDL, a lipoprotein preventing arteriosclerosis and cardiovascular disease progression." (PMID 24646941, 2014).
cerebrovascular disease (5 papers, 2017 to 2025). "Although the roles of ABCA1 and APOA5 in lipid regulation are well-documented, their specific interactions with dietary components in modulating cardio-cerebrovascular disease risk remain underexplored." (PMID 40077648, 2025). "Loss-of-function mutation in ABCA1 is found to be involved in familial HDL-deficiency, low ApoE plasma levels and a higher risk for AD and cerebrovascular disease." (PMID 36138870, 2022).
chronic obstructive pulmonary disease (5 papers, 2020 to 2023). A chronic and progressive lung disorder characterized by the loss of elasticity of the bronchial tree and the air sacs, destruction of the air sacs wall, thickening of the bronchial wall, and mucous accumulation in the bronchial tree. "Additionally, an AITC-induced reversal of ABCA1/G1 downregulation was observed in the rat alveolar macrophage cell line NR8383 challenged to a cigarette smoke extract (CSE) and in the lung tissues of chronic obstructive pulmonary disease (COPO) rats." (PMID 37432260, 2023).
colitis (5 papers, 2021 to 2024). Inflammation of the colon. "Moreover, SR‐B1 deficiency reduced the LDL‐R level and increased the ABCA1 level of colitis‐induced CRC." (PMID 37766594, 2023).
ischemia (5 papers, 2018 to 2025). A hypoperfusion of the BLOOD through an organ or tissue caused by a PATHOLOGIC CONSTRICTION or obstruction of its BLOOD VESSELS, or an absence of BLOOD CIRCULATION. "The LXR agonist TO-901317, known for its potent induction of ABCA1, has previously been shown to enhance oligodendrocyte proliferation, differentiation, and maturation, and to alleviate ischemia and lysolecithin-induced demyelination." (PMID 38741181, 2024). "To investigate the change of ABCA1 expression in RGCs after ischemia-reperfusion, we used a mouse model of ischemia induced by acute IOP elevation." (PMID 30364320, 2018).
liver cancer (5 papers, 2018 to 2025). An epithelial or non-epithelial malignant neoplasm that arises from the liver. "Our wet lab experiments corroborate the bioinformatic findings, providing robust evidence for the role of ABCA1 in liver cancer." (PMID 39749197, 2024). "Our result was similar to the study mentioned earlier conducted on mice: the deletion of the miR-148 harms hepatic cancer and lipid metabolism by targeting different genes, including ABCA1, and PGC1α." (PMID 36292712, 2022).
Nephropathy (5 papers, 2011 to 2025). A nonspecific term referring to disease or damage of the kidneys. "Further evaluation of two compounds (Cpd A and Cpd G) showed that they induced ABCA1 and cholesterol efflux from podocytes in vitro and normalized proteinuria and prevented renal function decline in mouse models of proteinuric kidney disease: Adriamycin-induced nephropathy and Alport Syndrome." (PMID 34341345, 2021). "Protein expressions of ABCA1, ABCG1 and SR-BI were significantly reduced in the kidneys from diabetic animals with the greatest reduction seen in mice with nephropathy." (PMID 25181357, 2014). "Histological examination revealed that ABCA1, ABCG1 and SR-BI were mainly expressed in renal tubules, and there was a marked reduction in all three cholesterol transporters in diabetic mice especially in the group with nephropathy." (PMID 25181357, 2014). "In conclusion, the expression of ABCA1, ABCG1 and SR-BI in mesangial cells and tubular cells were significantly decreased under hyperglycemic conditions in vitro, and renal expression of these cholesterol transporters was reduced in diabetic mice with nephropathy." (PMID 25181357, 2014).
osteosarcoma (5 papers, 2020 to 2025). A usually aggressive malignant bone-forming mesenchymal neoplasm, predominantly affecting adolescents and young adults. "Overall, these data demonstrate that ABCB1 is high and ABCA1 is low in doxorubicin-resistant osteosarcoma cells." (PMID 32155954, 2020). "In humanized mice, NZ reduced the growth of chemo-immune-resistant osteosarcomas, increased intratumor necro-apoptosis, and ABCA1/ABCB1 ratio and Vγ9Vδ2 T-cell infiltration." (PMID 32155954, 2020). "In conclusion, we demonstrated that ABCB1 and ABCA1 are inversely expressed in doxorubicin-sensitive and doxorubicin-resistant osteosarcoma cells." (PMID 32155954, 2020). "The role of ABCA1 was attributed to its control of cholesterol homeostasis and efflux, a function that was maintained in the osteosarcoma cell lines examined in the present work." (PMID 32155954, 2020). "A very recent analysis of the downstream signaling of parathyroid hormone receptor 1 identified ABCA1 as a putative gene important in osteosarcoma progression." (PMID 32155954, 2020). "To address this question, we examined the expression levels and the molecular circuitries regulating ABCA1 in human osteosarcoma cells with different levels of ABCB1." (PMID 32155954, 2020). "This experimental set demonstrates that ABCA1 is directly involved in IPP transport in osteosarcoma cells." (PMID 32155954, 2020). "ABCA1 regulates the immune sensitivity of osteosarcoma cells." (PMID 35837087, 2022). "Moreover, the ABCB1: ABCA1 ratio was reportedly upregulated in osteosarcoma cells and positively correlated with a higher probability of relapse." (PMID 35837087, 2022). "Comparison of mRNA gene expression level in osteosarcoma and human normal muscle tissue samples showed that expression of ABCA1 was significantly higher in osteosarcoma compared either to normal muscle (Asmann series; p < 0.001) or to normal skeletal muscle (Gordon series; p < 0.05)." (PMID 32155954, 2020). "We found that ABCB1 and ABCA1 are inversely expressed in osteosarcoma cells." (PMID 32155954, 2020). "Indeed, a reduced efflux of cholesterol in osteosarcoma doxorubicin-resistant cells, that are characterized by low levels of ABCA1 and high synthesis of cholesterol, may determine an increased accumulation of cholesterol in the plasma membrane." (PMID 32155954, 2020). "Our gain- and loss-of-function experiments provided the demonstration that ABCA1 transports IPP and modulates the activity of Vγ9Vδ2 T-lymphocytes in osteosarcoma, as it does in antigen-presenting cells." (PMID 32155954, 2020). "Unexpectedly, in osteosarcoma cells with acquired resistance to doxorubicin and high levels of ABCB1, the amount of ABCA1 was reduced." (PMID 32155954, 2020). "We next investigated if ABCA1 mediates the efflux of IPP and the anti-tumor activity of Vγ9δ2 T-lymphocytes in osteosarcoma, as it does in dendritic cells." (PMID 32155954, 2020). "The prognostic meaning of ABCA1 and its physiological or pathological function in osteosarcoma has never been studied." (PMID 32155954, 2020). "Despite its well-known role as a prognostic factor in different solid tumors, no reports documented a clinical role for ABCA1 in osteosarcoma." (PMID 32155954, 2020). "In this work, we analyzed how ABCA1 and ABCB1 are regulated in osteosarcoma, and if increasing the ABCA1-dependent activation of Vγ9Vδ2 T-cells could be an effective strategy against ABCB1-expressing osteosarcoma." (PMID 32155954, 2020). "In a limited series of high-grade osteosarcomas, a non-significant trend of the high ABCB1 mRNA levels or the low ABCA1 mRNA levels at diagnosis toward a worse relapse-free survival." (PMID 32155954, 2020).
pancreatic cancer (5 papers, 2020 to 2025). "Since the substrate sets of ABCA1-2, ABCB1, ABCC5, and ABCG2 overlap, the general effect of SOX9 suppression on overall or partial drug resistance of pancreatic cancer cells in context of these ABC proteins cannot be predicted with certainty." (PMID 40141294, 2025). "Although SR-B1 is highly expressed in the applied pancreatic-cancer cell lines and significantly contributes to HDL-mediated cholesterol flux, forced efflux via ABCA1 increases the antitumor activity of those particles (see graphical abstract)." (PMID 35577388, 2022). "We also compared the expression of LXRβ and known target genes SREBF1, ABCA1, ABCG1, FASN, and SCD in pancreatic cancer tissue to normal pancreas tissue and found that transcript levels of LXRβ and its target genes are elevated in the tumor tissues." (PMID 33348693, 2020). "Consistently, we identified ABCA1 as a robustly upregulated gene in both MIA PaCa‐2 and BXPC3 cells following GW3965 treatment, suggesting that the regulation of cholesterol transport is a mechanism by which GW3965 controls cell proliferation in pancreatic cancer." (PMID 38089448, 2022). "Interestingly, in silico Kaplan–Meier analyses with the UCSC Xena database neither revealed a correlation of patient overall survival with SCARB1 (SR-B1) nor with ABCA1 expression in the Genomic data commons (GDC) The Cancer Genome Atlas TCGA pancreatic-cancer cohort." (PMID 35577388, 2022).
Sepsis (5 papers, 2012 to 2025). Sepsis is defined as life-threatening organ dysfunction caused by a dysregulated host response to infection. "Expression of cholesterol efflux transporter Abca1 was unaffected by illness and of Abcg1 increased with sepsis." (PMID 34274000, 2021). "UC-HDL from patients with sepsis, reflecting a severe inflammatory state, showed a similar ABCA1-mediated cholesterol efflux potential from cholesterol-laden fibroblast cells in the presence of a LXR agonist." (PMID 22611487, 2012). "Overexpression of circRNA itchy E3 ubiquitin protein ligase (circ-ITCH) can improve renal function in SA-AKI mice and regulate oxidative stress and mitochondrial dysfunction in sepsis-induced AKI through the miR-214-3p/ABCA1 pathway, further enriching the pathophysiology of SA-AKI." (PMID 40766066, 2025).
bladder cancer (4 papers, 2017 to 2023). "Importantly, A1−M/−M mice were also notable for being resistant to MB49 bladder cancer, suggesting that the protective mechanism triggered by loss of myeloid ABCA1 may be effective against a wide spectrum of tumors." (PMID 29069761, 2017).
chronic kidney disease (4 papers, 2014 to 2024). Impairment of the renal function secondary to chronic kidney damage persisting for three or more months. "In contrast, accumulation of lipid in the remnant kidney in rats with chronic renal failure induced by 5/6 nephrectomy was accompanied by up-regulation of both ABCA1 and SR-BI." (PMID 25181357, 2014). "According to previously published results in chronic kidney disease patients, such inflammatory mediators as lipopolysaccharide and cytokines inhibit cholesterol efflux from cells by decreasing expression of the adenosine triphosphate–binding cassette A1 (ABCA1) gene." (PMID 38302546, 2024).
endothelial dysfunction (4 papers, 2020 to 2025). In vascular diseases, endothelial dysfunction is a systemic pathological state of the endothelium (the inner lining of blood vessels) and can be broadly defined as an imbalance between vasodilating and vasoconstricting substances produced by (or acting on) the endothelium. "Previous studies have demonstrated that ABCA1 expression safeguards against endothelial dysfunction." (PMID 39621727, 2024). "Previous researches suggest that ABCA1 expression in GEnCs may help to prevent endothelial dysfunction." (PMID 39621727, 2024).
familial hypoalphalipoproteinemia (4 papers, 2009 to 2023). "It is known to be associated with a reduced HDL cholesterol and familial hypoalphalipoproteinemia (FHA), indicating that ABCA1 polymorphism might affect lipids metabolism." (PMID 36444680, 2023).
fish eye disease (4 papers, 2007 to 2022). Fish eye disease (FED) is a form of genetic LCAT (lecithin-cholesterol acyltransferase) deficiency characterized clinically by corneal opacifications, and biochemically by significantly reduced HDL cholesterol and partial LCAT enzyme deficiency. "We also report here cholesterol and phospholipid accumulation in a cornea from a patient with ABCA1 deficiency and LCAT deficiency (Fish-eye disease)." (PMID 31779197, 2019).
HIV-1 infection (4 papers, 2012 to 2025). The type species of lentivirus and the etiologic agent of acquired immunodeficiency syndrome (AIDS). "HIV-1 infection is also known to interfere with cholesterol metabolism by downregulating the cholesterol transporter ABCA1 (ATP-binding cassette transporter A1), a critical regulator of cellular cholesterol efflux." (PMID 40699766, 2025). "ATRA and LXR-agonist TO-901317 have synergistic effect on the induction of ABCA1 expression as well as anti-HIV-1 infection in CD4+ T cells." (PMID 22676378, 2012). "Our results show that ATRA mediated induction of ABCA1 and cholesterol efflux in activated T cells leads to the inhibition of HIV-1 infection." (PMID 22676378, 2012). "ABCA1 mediated cholesterol efflux has been shown to inhibit HIV-1 infection in macrophages." (PMID 22676378, 2012). "NPC1 protein expression could also be decreased upon HIV-1 infection in a manner similar to ABCA1 downregulation." (PMID 22273177, 2012). "Furthermore, ATRA and TO-901317, an LXR agonist, functioned synergistically to further enhance ABCA1 expression and inhibit HIV-1 infection in T cells." (PMID 22676378, 2012). "Interestingly, the effects of Nef on ABCA1 during HIV-1 infection may not be restricted to infected cells, as exogenous Nef taken up by cells was also shown to be active in ABCA1 downregulation and cholesterol efflux reduction." (PMID 34307340, 2021).
liver disease (4 papers, 2008 to 2022). "We aimed to analyze the role of ABCA1 polymorphism R1587K (rs2230808) in modulating the biochemical parameters of lipid metabolism and liver function and its association with liver disease severity, according to gender." (PMID 36421770, 2022). "We aimed to analyze the role of ABCA1 polymorphism R1587K (rs2230808) in modulating biochemical parameters of lipid metabolism and liver function and its association with liver disease severity, according to gender." (PMID 36421770, 2022). "Additional research is needed to conclude the role of ABCA1 in liver disease including its association with NAFLD/NASH." (PMID 33562440, 2021).
lupus (4 papers, 2018 to 2025). "This is elegantly demonstrated in mice with Abca1/g1 deficiency in dendritic cells (DCs) that have a lupus-like phenotype." (PMID 30072988, 2018). "In systemic lupus erythematosus, defective efferocytosis is closely associated with aberrations in PPAR signaling, LXR signaling, ABCA1 expression, and C1q membrane protein deficiency." (PMID 40458640, 2025). "Nineteen probes for 16 lupus-relevant genes (Abca1, Apobec3, Ccr7, Ceacam3, Ets1, Foxp3, Hdac1, Ifng, Irf9, Itgam, Jhdm1d, Mmp9, Oscar, Slc4a1, Tbx21, and Tlr7) were identified from the database of male murine spleen." (PMID 30246031, 2018). "The LXR agonist T0901317 inhibited type I interferon and increased ABCA1 in lupus patients’ monocytes and in murine peritoneal macrophages." (PMID 29456535, 2018). "Similarly, lupus patients’ monocytes exhibited low LXRα/ABCA1 and high HIF1α vs. controls." (PMID 29456535, 2018). "In both pristane-induced lupus and SLE patients, expression of the LXR-regulated gene ABCA1 was impaired at both the RNA and protein level." (PMID 29456535, 2018). "Lupus and control Mφ did not exhibit substantially different Nr1h3 gene expression, suggesting that the low Abca1 levels in lupus mice reflect impaired activation of LXR protein rather than low Nr3h1 mRNA levels." (PMID 29456535, 2018). "As in pristane-induced lupus, NR1H3 and ABCA1 expression correlated in humans." (PMID 29456535, 2018).
neuroblastoma (4 papers, 2013 to 2024). Neuroblastoma (NB) is the most common solid, extracranial childhood tumor. "In neuroblastoma and liver cells, miR-106b prevented Aβ clearance by suppressing ABCA1 expression, while inhibition of miR-33a increased lipidated ApoE levels, and reduced Aβ levels mediated by the re-expression of ABCA1." (PMID 31749959, 2019). "Additionally, overexpression of miR-106b in both mouse neuroblastoma N2A and human hepatocyte HepG2 cells promotes Aβ secretion and impairs its clearance by targeting the 3’UTR of the ATP-binding cassette transporter A1 (ABCA1) and suppressing its expression." (PMID 38726308, 2024).